HOXC-AS2 (HOXC cluster antisense RNA 2)
Gene: Long non-coding RNA gene on chromosome 12 (53,993,810 to 53,996,785, reverse strand). Ensembl gene ENSG00000250133.
Diseases named in the same sentence as HOXC-AS2 in open-access papers:
HOXC-AS2 is named in the same sentence as 9 diseases in open-access papers, as found by Europe PMC text mining. Sharing a sentence is not in itself a finding about the gene and the disease. The quoted sentences say what the papers report.
glioma (3 papers, 2023 to 2024). A benign or malignant brain and spinal cord tumor that arises from glial cells (astrocytes, oligodendrocytes, ependymal cells). "Among them, LncRNA HOXC-AS2 is considered a novel tumor-associated LncRNA, and studies have shown that HOXC-AS2 may be related to glioma, gastric adenocarcinoma, digestive cancer, and non-small-cell lung cancer (NSCLC)." (PMID 38542388, 2024). "In glioma cells, HOXC-AS2 sponged miR-876-5p to release ZEB1 expression, whereas ZEB1 regulated HOXC-AS2 at the transcriptional level by binding with its promoter." (PMID 37239035, 2023).
non-small cell lung carcinoma (3 papers, 2023 to 2024). A group of at least three distinct histological types of lung cancer, including non-small cell squamous cell carcinoma, adenocarcinoma, and large cell carcinoma. "Recent studies have shown that HOXC-AS2 is closely related to the progression and metastasis of endometrial cancer and non-small cell lung cancer (NSCLC) through a competing endogenous RNA (ceRNA) mechanism." (PMID 37944249, 2023).
endometrial cancer (1 paper, 2023). Primary or metastatic malignant neoplasm involving the endometrium (mucous membrane that lines the endometrial cavity). "HOXC-AS2 also regulates endometrial cancer progression, a finding that demonstrates that HOXC-AS2 can play a cancer-promoting role through a ceRNA mechanism." (PMID 37944249, 2023).
hypopharyngeal carcinoma (1 paper, 2023). Carcinoma, predominantly squamous cell, arising from the epithelial cells of the hypopharynx. "Our results show that HOXC-AS2 can be used as a diagnostic marker for and a potential therapeutic target in hypopharyngeal cancer." (PMID 37944249, 2023). "The mRNA expression of HOXC-AS2 and related genes was measured by qRT-PCR, and the biological function of HOXC-AS2 in hypopharyngeal carcinoma was demonstrated by gain- and loss-of-function experiments." (PMID 37944249, 2023). "In summary, the results of these experiments indicated that HOXC-AS2 is highly expressed in hypopharyngeal carcinoma and is localized mainly in the cytoplasm." (PMID 37944249, 2023). "Based on the results of the previous experiments, we further explored the role of HOXC-AS2 in hypopharyngeal carcinoma through animal experiments." (PMID 37944249, 2023). "The expression of HOXC-AS2 in hypopharyngeal cancer tissues was significantly increased compared with that in normal tissues." (PMID 37944249, 2023). "Then, through verification assays in cell lines and by FISH, we found that in addition to its known function, HOXC-AS2 is upregulated in hypopharyngeal cancer and primarily localized in the cytoplasm of hypopharyngeal cancer cells." (PMID 37944249, 2023). "Functionally, HOXC-AS2 overexpression can promote the viability, proliferation, migration and invasion of hypopharyngeal cancer cells and facilitate hypopharyngeal cancer progression." (PMID 37944249, 2023). "The lncRNA sequencing results indicated that HOXC-AS2 was highly expressed in human hypopharyngeal cancer tissues." (PMID 37944249, 2023). "In conclusion, our findings suggest that HOXC-AS2 regulates the progression of hypopharyngeal cancer by regulating autophagy and is abnormally highly expressed in hypopharyngeal cancer tissues." (PMID 37944249, 2023). "HOXC-AS2 and P62 expression was significantly upregulated in hypopharyngeal cancer tissues compared with normal hypopharyngeal tissues, while HMOX1 expression was decreased." (PMID 37944249, 2023). "Therefore, we concluded that HOXC-AS2 plays a very important role in the progression of hypopharyngeal cancer." (PMID 37944249, 2023). "To further confirm whether HOXC-AS2 regulates the progression of hypopharyngeal cancer by regulating autophagy, we knocked down HOXC-AS2 in Detroit-562 cells and observed the formation of autophagosomes by transmission electron microscopy." (PMID 37944249, 2023). "The previous findings indicated that HOXC-AS2 plays a vital role in the formation and progression of hypopharyngeal cancer, but the related mechanism remains unclear and needs further exploration." (PMID 37944249, 2023). "In this study, we found by transmission electron microscopy that autophagosome formation in hypopharyngeal cancer cells was significantly increased when HOXC-AS2 was knocked down, a finding that provided expanded evidence supporting the results of our subcellular localization experiment." (PMID 37944249, 2023). "Analysis of the lncRNA sequencing data indicated that HOXC-AS2 had the highest expression level in hypopharyngeal cancer tissues, and further analysis of specimens from clinical cases also confirmed that HOXC-AS2 was highly expressed in hypopharyngeal cancer tissues." (PMID 37944249, 2023). "Thus, we speculated that HOXC-AS2 also plays an important role in the progression of hypopharyngeal cancer." (PMID 37944249, 2023). "HOXC-AS2 may become a new target for the diagnosis and treatment of hypopharyngeal cancer." (PMID 37944249, 2023). "In summary, we confirmed that HOXC-AS2 can affect the expression of HMOX1 by regulating the NF-KB signaling pathway, thus regulating autophagy and the progression of hypopharyngeal cancer." (PMID 37944249, 2023). "To date, the mechanism of action of HOXC-AS2 in hypopharyngeal carcinoma has not been studied." (PMID 37944249, 2023). "To date, the role of HOXC-AS2 in hypopharyngeal carcinoma has not been explored." (PMID 37944249, 2023).
hypopharyngeal carcinoma (continued). "In conclusion, HOXC-AS2 can bind to the p62 protein to activate the NF-KB signaling pathway, thereby regulating the expression of HMOX1 and ultimately affecting autophagy in hypopharyngeal cancer cells to facilitate the formation and progression of hypopharyngeal cancer." (PMID 37944249, 2023).
tumor (3 papers, 2023 to 2024). "Based on the current literature, we determined that HOXC-AS2 is an oncogene that can regulate apoptosis, EMT and pyroptosis in tumor cells." (PMID 37944249, 2023). "AC093895.1, CASC9, HOXC-AS2, and LINC01980 may be involved in tumor progression, and the molecular mechanism remains to be further verified." (PMID 36445051, 2023).
HOXC-AS2 also shares sentences with these, for which no sentence is quoted: cancer (3 papers); bladder cancer (1); gastric adenocarcinoma (1); papillary thyroid cancer (1).